GFAP (glial fibrillary acidic protein)
Diseases named in the same sentence as GFAP in open-access papers (continued):
Sharing a sentence is not in itself a finding about the gene and the disease.
autoimmune disease (15 papers, 2012 to 2025). A disorder resulting from loss of function or tissue destruction of an organ or multiple organs, arising from humoral or cellular immune responses of the individual to their own tissue constituents. "More diagnostic clues are required to develop early consensus on GFAP autoimmune diseases." (PMID 37205100, 2023). "Autoimmune glial fibrillary acidic protein (GFAP) astrocytopathy is a recently emerging autoimmune disease of the central nervous system (CNS); GFAP astrocytopathy is characterized by optic neuritis and meningoencephalomyelitis." (PMID 38699059, 2024). "Autoimmune glial fibrillary acidic protein (GFAP) astrocytopathy is a rare autoimmune disease, which is characterized by the immune system attacking astrocytes in the central nervous system, resulting in inflammation and damage to the nervous system." (PMID 39464885, 2024). "Autoimmune glial fibrillary acidic protein (GFAP) astrocytopathy is an autoimmune disease that involves GFAP autoantibodies in the cerebrospinal fluid (CSF) and serum." (PMID 39328614, 2024). "In conjunction with this study, we consider RESLES to be a specific clinical imaging finding of GFAP-A, implying that patients with RESLES should also be considered for a diagnosis of GFAP autoimmune disease." (PMID 37205100, 2023). "Autoimmune glial fibrillary acidic protein (GFAP) astrocytopathy is a novel autoimmune disease of central nervous system (CNS)." (PMID 37458208, 2023). "Glial fibrillary acidic protein (GFAP) astrocytopathy is an autoimmune disease affecting the central nervous system (CNS)." (PMID 36371153, 2022). "Autoimmune glial fibrillary acidic protein (GFAP) astrocytopathy is an increasingly recognized type of steroid-responsive autoimmune disease of the nervous system." (PMID 34160439, 2021). "Autoimmune glial fibrillary acidic protein (GFAP) astrocytopathy is increasingly recognized as a form of a nervous system steroid-responsive autoimmune disease." (PMID 34160439, 2021). "Glial fibrillary acidic protein (GFAP) has been shown to be upregulated in autoimmune diseases where TNFα and IL-1ßwere overexpressed, causing glial scarring as the astrocytes interact with neural injuries." (PMID 26648846, 2015). "CNS insults, including autoimmune disease, initiate rapid astrocyte activation characterized by cellular hypertrophy and increased intermediate filament glial fibrillary acidic protein (GFAP) expression." (PMID 22848713, 2012). "Despite extensive investigation ruling out infectious and autoimmune diseases, bone marrow biopsy, and CSF cytology, elevated levels of anti-GFAP antibodies were detected early in the disease and decreased during remission, as observed using a cell-based assay." (PMID 39328614, 2024). "Preoperative multidisciplinary consensus deemed the spinal cord lesions diagnostically equivocal, given the concurrent GFAP-IgG and AQP4-IgG positivity raising suspicion of autoimmune disease." (PMID 40688088, 2025). "Autoimmune glial fibrillary acidic protein (GFAP) astrocytopathy is an autoimmune disease, and there have been no reports of a Brucella infection, leading to GFAP astrocytopathy." (PMID 35990675, 2022). "Additionally, integrating GFAP into biomarker panels with CRP, IL-6, and ANCA could improve diagnosis and treatment monitoring in autoimmune diseases." (PMID 39459426, 2024).
Huntington disease (15 papers, 2007 to 2026). Huntington disease (HD) is a rare neurodegenerative disorder of the central nervous system characterized by unwanted choreatic movements, behavioral and psychiatric disturbances and dementia. "Even though astrocytes do not express CB2 receptors, genetic deletion of CB2 receptors results in enhanced GFAP expression in rodent models of neuropathic pain and Huntington's disease." (PMID 20531936, 2010). "In particular, our previous studies assessing these biomarkers in saliva samples from Huntington’s disease patients observed detection rates of 100 %, 88.4 %, 81.1 % and 98.9 %, for YKL-40, NfL, GFAP and total tau, respectively." (PMID 40494737, 2025). "For example, in the human brain tissues of patients who died with Huntington’s disease, a significant increase in the levels of proliferating cell nuclear antigen (PCNA), beta III-tubulin (a neuronal marker), and glial fibrillary acidic protein (GFAP- a glial cell marker) can be found." (PMID 34070012, 2021).
teratoma (15 papers, 2013 to 2026). A non-seminomatous germ cell tumor characterized by the presence of various tissues which correspond to the different germinal layers (endoderm, mesoderm, and ectoderm). "Co-immunostaining with GluN1 and GFAP antibodies demonstrated that both proteins were co-expressed by astrocytes in NMDAR-E associated teratomas and in control teratomas." (PMID 30857565, 2019). "In a previously published case of a teratoma in a duck, immunohistochemistry revealed GFAP and NSE reactive tissue components." (PMID 40217475, 2025). "Analysis of tumor tissue from one Caucasian patient revealed teratoma-contained neuroectodermal tissue with the expression of GFAP." (PMID 35651803, 2022). "Small clusters of human cells staining positive for the ectodermal markers, neuron-specific class III beta-tubulin (TUJ-1) and glial fibrillary acidic protein (GFAP), were found in most teratomas." (PMID 26777057, 2016). "Increased GFAP expression has been attributed to neuroectodermal component in teratomas." (PMID 34831039, 2021). "In addition to well-differentiated epidermis and dermis with sebaceous glands, eccrine glands and hair follicles, the teratoma-contained neuroectodermal tissue with expression of glial fibrillary acidic protein (GFAP)." (PMID 33078290, 2021). "In all of these patients, teratomas revealed the expression of AQP4 and GFAP in areas containing neuroglial tissue." (PMID 35651803, 2022). "In order to establish an unequivocal diagnosis of immature teratoma, 3 antibodies (SALL4, GFAP, Ki-67) were employed to distinguish primitive neuroepithelial tissues from mature counterparts." (PMID 36309682, 2022). "Three germ layer derivatives were also observed in the teratoma by immunofluorescent staining with three germ layer markers, Foxa2 for endoderm, α-actinin and α-SMA for mesoderm, Tuj1 and GFAP for ectoderm." (PMID 33608671, 2021). "The teratoma also stained with α-SMA, AFP and GFAP (a marker of the ectoderm), respectively, to further demonstrated the differentiation ability." (PMID 27025901, 2016). "GFAP antibody, AQP4 antibody, and NMDAR antibody are expressed in teratoma." (PMID 39464885, 2024). "In the teratoma, the neuroectodermal tissue expressed Glial fibrillary acidic protein (GFAP), S100 protein, Epithelial membrane antigen (EMA) and Cytokeratin 34 beta E12 (Ck34beta E12), wheares the implants expressed only GFAP and S100 protein." (PMID 23590935, 2013). "GFAP is commonly considered as a marker for mature and differentiated astrocytes, which shows high immunoreactivity in mature glial cells but not in primitive neuroepithelial tissues of immature teratoma." (PMID 36309682, 2022).
astrocytic tumor (14 papers, 2012 to 2025). A glial tumor of the brain or spinal cord showing astrocytic differentiation. "GFAP levels in astrocytic tumors correlate with tumor grade and lethality, and serum levels of GFAP and GFAP-positive circulating tumors cells are diagnostic of tumor grade and lethality." (PMID 26689994, 2016). "To reconfirm, 2-BromoPalmitate (2-BP, a general inhibitor of protein palmitoylation) was incubated with human astroglioma cell line U251, it was found that 2-BP can inhibit the level of palmitoylated GFAP (palm-GFAP) gradually in a manner of incubation time." (PMID 33753498, 2021). "Next, to specifically evaluate the roles of palmitoylation, GFAP and GFAP-C291A were expressed in both U251 and U87 (human astroglioma) cell lines." (PMID 33753498, 2021). "In contrast, looking at GBM tissue, double staining of RPS27 with GFAP was obvious, indicating the astrocytic tumor cells." (PMID 32349320, 2020). "All tumors expressed GFAP (glial fibrillary acidic protein) and vimentin, markers for astrocytic tumors." (PMID 27664151, 2017). "In original tumor material, with double immunofluorescence we confirmed that receptor expression occurred in GFAP-positive astrocytic tumor cells as well as on CD68/CD163-positive microglia/macrophages." (PMID 25894595, 2015). "Immunohistochemical detection of glial fibrillary acidic protein (GFAP) additionally helps identify astrocytic neoplasms." (PMID 22844452, 2012). "Antibodies directed to GFAP are frequently used in the diagnosis of astrocytic tumors." (PMID 24086629, 2013).
cerebrovascular disease (14 papers, 2015 to 2025). "Across all neurodegenerative and cerebrovascular disease participants pooled together, GFAP, NfL, and p‐tau181 were found to be associated with most cognitive domains at baseline (raw data presented)." (PMID 38105605, 2024). "Participants in the high IL‐6 subgroup also exhibited a stronger association between cerebrovascular disease and levels of NfL and GFAP than those in the low IL‐6 subgroup." (PMID 38717935, 2024). "In addition to the core AD pathologies, we identified significant associations of GFAP expression with other neuropathologies, including cerebrovascular disease, TDP-43, and Lewy body pathologies." (PMID 39580758, 2024). "Reactive astrocytes are present across multiple neurodegenerative diseases, but plasma GFAP correlates more consistently with AD neuropathology (particularly brain amyloid) than other proteinopathies or cerebrovascular disease." (PMID 40911721, 2025). "Instead, the temporal dynamics of GFAP and β-syn in cerebrovascular diseases, as well as their possible utility when measured at later timepoints, remains still unexplored." (PMID 38017278, 2023). "Patients with CKD stages 3 and 4, without cerebrovascular disease, had elevated plasma concentrations of NfL, p-Tau231 and GFAP compared with healthy controls, and mGFR was inversely correlated to plasma levels of these biomarkers." (PMID 40346521, 2025). "Only three LBSD autopsy patients had significant cerebrovascular disease, and we were not able to assess how GFAP and p‐tau181 levels would be altered by moderate or high vascular disease in this study." (PMID 37000892, 2023).
hematoma (14 papers, 2021 to 2026). A hematoma is a collection of blood from a vascular structure into an extravascular space. "HSD➔ND chimeras also had larger hematoma volumes, exacerbated neuron loss, and more GFAP+ cells on day 10 post‐ICH." (PMID 37965920, 2023). "Multiple studies confirmed a strong correlation between hematoma volume and GFAP levels in serum or plasma." (PMID 38581002, 2024). "Sensitivity was 61.5% when assessed against an ICH volume > 15 mL, showing that GFAP increases as a function of hematoma size." (PMID 37511304, 2023). "The diagnostic accuracy seems to be directly proportional to the size of the hematoma, where for larger volumes of haemorrhage, there are greater increases in GFAP." (PMID 37511304, 2023). "On the other hand, 50 mg/kg C-DIM12 did not affect the accumulation of glial fibrillary acidic protein (GFAP)-immunopositive astrocytes in the peri-hematoma region at the same time point." (PMID 35773404, 2022). "Subsequent analysis of immunofluorescence and Western blotting revealed that the administration of etrolizumab resulted in increased activation of microglia/macrophages and astrocytes, as evidenced by Iba-1 and GFAP staining, surrounding the hematoma 3 d after ICH." (PMID 39659582, 2024). "In addition, 1400 W significantly suppressed the accumulation of GFAP-positive astrocytes in the peri-hematoma region at 72 h after induction of ICH." (PMID 35773404, 2022). "Notably, reactive astrocytes demarcate the hematoma lesion and can be discerned by overexpression of GFAP along with time after ICH." (PMID 34035344, 2021). "In addition, the number of Iba1-positive cells activated increased from 3 h to 3 days (55.20 ± 8.04 vs 0.00 ± 0.00; P < 0.001) and the intensity levels of GFAP were induced at 3 days (19.49 ± 2.76 vs 4.09 ± 1.56; P < 0.001) around hematoma after ICH compared with the sham group." (PMID 37620888, 2023). "The effect of NR on glial cells was evaluated by detecting the activation of glial fibrillary acidic protein (GFAP) and ionized calcium-binding adapter molecule (Iba-1) in the peri-hematoma tissues." (PMID 38981960, 2025). "A mass of activated astrocytes, detected by the colocalization of GFAP and CSPG, aggregated at the peri‐hematoma region after ICH." (PMID 36550632, 2023). "In conclusion, HBO improves consciousness, cognitive function, and prognosis in patients with severe or moderate TBI through decreasing TBI-induced hematoma volumes, promoting the recovery of EEG rhythms, and modulating the expression of serum NSE, S100β, GFAP, BDNF, NGF, and VEGF." (PMID 36034283, 2022). "HBO may be an effective treatment for patients with TBI to improve consciousness, cognitive function and prognosis through decreasing TBI-induced hematoma volumes, promoting the recovery of EEG rhythm, and modulating the expression of serum NSE, S100β, GFAP, BDNF, NGF, and VEGF." (PMID 36034283, 2022).
pilocytic astrocytoma (14 papers, 2013 to 2025). Pilocytic astrocytoma is a rare subtype of low-grade glioma of the central nervous system characterized by a well circumscribed, often cystic, brain tumor with a discrete mural nodule and long, hair-like projections that extend from the neoplastic astrocytes. "As the available clinical information does not include specific information about the patients’ genetic alterations, the difference in GFAP staining in NF1-associated versus non-NF1-associated pilocytic astrocytomas cannot be assessed." (PMID 35885538, 2022). "Biopsy was performed in one patient; this analysis revealed a pilocytic astrocytoma (case 5) with strongly positive staining for GFAP." (PMID 38376530, 2024). "Strong and diffuse GFAP immunostaining in most neoplastic cells is a consistent finding in pilocytic astrocytoma." (PMID 35885538, 2022). "A two-tailed chi-square test signified that the GFAP score for pilocytic astrocytoma significantly differs from the GFAP scores for other neoplasms (X2 = 34.63, df = 1, p = 0.0001)." (PMID 35885538, 2022). "GFAP immunostaining was strongly and diffusely positive in both the solid fibrillary component and the oligodendrocyte-like component in all pilocytic astrocytoma cases." (PMID 35885538, 2022). "The result in this study is consistent with their observations, as all pilocytic astrocytomas had a GFAP score of 4 (which corresponds to category 4)." (PMID 35885538, 2022). "In the setting of CNS tumors with oligodendrocyte-like areas, diffuse and strong cytoplasmic GFAP immunostaining in these cells favor the diagnosis of pilocytic astrocytoma." (PMID 35885538, 2022). "All 26 cases (16 males and 10 females) of pilocytic astrocytoma showed strong and diffuse (score 4) GFAP immunostaining in the neoplastic cells of both the solid fibrillary and oligodendrocyte-like components." (PMID 35885538, 2022). "As this study has a limited number of pilocytic astrocytoma cases, the possibility of pilocytic astrocytomas with a lower GFAP score cannot be excluded." (PMID 35885538, 2022). "The diffuse and strong GFAP immunostaining in the round oligodendrocyte-like neoplastic cells in pilocytic astrocytoma was in the form of a thin rim of perinuclear cytoplasmic staining." (PMID 35885538, 2022). "In this work, diffuse and strong GFAP immunostaining in more than 75% (score 4) of neoplastic cells was consistent in all cases of pilocytic astrocytoma." (PMID 35885538, 2022). "In the setting of tumors with predominant oligodendrocyte-like areas, the GFAP immunostaining score and pattern help distinguish pilocytic astrocytoma from its mimickers." (PMID 35885538, 2022). "Cases #1–3 were pathologically diagnosed as WHO grade I pilocytic astrocytoma based on evidence of a biphasic pattern of glial fibrillary acidic protein immunostaining and the existence of Rosenthal fibers." (PMID 34685506, 2021). "GFAP is known to be diffusely and strongly immunopositive in pilocytic astrocytoma." (PMID 35885538, 2022). "Therefore, this study aims to determine the utility of the GFAP immunostaining pattern in supporting the diagnosis of pilocytic astrocytoma in cases with a predominant oligodendrocyte-like component." (PMID 35885538, 2022). "In addition, the findings indicated the sensitivity of the GFAP score for pilocytic astrocytoma." (PMID 35885538, 2022). "The GFAP staining pattern of gliofibrillary oligodendrocytes was a perinuclear cytoplasmic rim, similar to the staining pattern in the oligodendrocyte-like cells in pilocytic astrocytoma, but pilocytic astrocytoma cells may show a cytoplasmic process." (PMID 35885538, 2022). "Pathology reported a Pilocytic astrocytoma WHO grade 1, with immunohistochemistry reporting a strongly positive Glial Fibrillary Acidic Protein (GFAP), a low Ki-67, and Neu N positive." (PMID 41357590, 2025). "Glial fibrillary acidic protein (GFAP) is diffusely and strongly immunopositive in pilocytic astrocytoma." (PMID 35885538, 2022).
pilocytic astrocytoma (continued). "The most convincing immunohistochemical staining was found with GFAP in the specimen ZNS212, labelled as pilocytic astrocytoma." (PMID 26252375, 2015). "Score 4 GFAP (more than 75%) staining in neoplastic cells in these areas is consistent with a diagnosis of pilocytic astrocytoma, whereas a lower GFAP score is not specific and does not distinguish between the tumors in the differential diagnoses." (PMID 35885538, 2022). "Glial fibrillary acidic protein (GFAP) immunohistochemistry (IHC) verified the chronic dense gliosis and showed no cystic or rarified areas (i.e., no features of pilocytic astrocytoma with compact and loose tissues)." (PMID 31845864, 2020). "Although, pilocytic astrocytoma is GFAP positive, it almost never stains for vimentin, which helps to discriminate it from tanycytic ependymoma." (PMID 23476839, 2013). "These tumors are considered to be more aggressive than pilocytic astrocytomas and immunohistochemically label strongly and diffusely for GFAP and vimentin but are negative for the neuronal markers synaptophysin, neurofilament, chromogranin and epithelial membrane antigen." (PMID 38983553, 2022). "The lack of pilocytic astrocytomas with a lower GFAP score in this study could be explained by the lower number of cases and the selective evaluation of oligodendrocyte-like components." (PMID 35885538, 2022).